IL6 (interleukin 6)
Diseases named in the same sentence as IL6 in open-access papers (continued):
Sharing a sentence is not in itself a finding about the gene and the disease.
tumor (continued). "These cells are recruited in response to IL-6, IL-10 and TGF-β secretion by the tumor cells to downregulate tumor antigen recognition, prevent T cell proliferation and inhibit cytotoxic T cell function." (PMID 35582566, 2019). "These tumor exosomes were also found to release pro-inflammatory cytokines IL-6 and tumor growth factor VEGF further enhancing its role in tumor growth." (PMID 31555295, 2019). "The proinflammatory cytokines IL-1, IL-6 and monocyte chemotactic protein-1 (MCP-1) are required for angiogenesis and tumour growth and promote the invasion and metastasis of cancer cells in animal models." (PMID 31639017, 2019). "In the tumor microenvironment, TGF-β, Chemokine 4/12 (CXCL4/12), interleukin-6 (IL-6) and tumor necrosis factor-α (TNF-α), etc. can enhance EMT." (PMID 31195692, 2019). "The increased level of IL-6 augments pro-angiogenic VEGF-A expression in classical monocytes, and thereby accelerates tumor metastasis." (PMID 31474975, 2019). "BMSCs can synthesize and secrete various cytokines to act on endothelial cells, such as VEGF, PDGF, bFGF, angiopoietin, IL-6, IL-8 and TGF-β, which promote tumor angiogenesis." (PMID 31864321, 2019). "TNF-α, IL-6 and TGF-β promote the production of IL-17 which affects chronic inflammatory responses and thus tumor development." (PMID 30642295, 2019). "By secreting cytokines such as IL-6, IL-18, TNF-α, TNF-β, IL-1β, IFN-γ and IL-23, arginase 1 (ARG1) and ECM-modifying enzymes into the TME, TAMs contribute to tumor cell growth, angiogenesis, invasion and metastasis." (PMID 30781344, 2019). "CAFs are also a source of IL6 in CRC, which in turn can increase VEGF secretion by adjacent fibroblasts and induce tumor angiogenesis in xenografted cancer cells." (PMID 31885581, 2019). "For instance, in pancreatic cancer, stromal HH/GLI signaling has been shown to induce IL6 expression, which in turn results in paracrine activation of STAT3 in the tumor cell compartment, thereby supporting cancer growth and survival." (PMID 31878932, 2019). "Interleukin-6 (IL-6) is the most important STAT3 activator and promotes tumor cell proliferation, survival, invasion, angiogenesis." (PMID 30606233, 2019). "Previous research findings indicated that combined targeting of IL-6/JAK/STAT pathway and PD-L1 resulted in restricted tumor growth in in vivo models, while in others, STAT3 targeting increased the efficacy of anti-PD1 mAb." (PMID 31581535, 2019). "Cytokines were measured in the BAL supernatant, and an increase in IL6 and IL10 content was observed in the 7 d tumor group." (PMID 31712726, 2019). "S. boulardii treatment reduced AOM/DSS-induced UC carcinogenesis in mice, as indicated by the reduced tumor load and reduced TNF-α and IL-6 levels in vivo, as well its effects on TNF-α and IL-6 activities in vitro." (PMID 31694526, 2019). "C26 cells stimulation by either sICAM-1 administration or co-culture with LSECs results in tumor cell secretion of inflammatory PGE2 and IL-6, VEGF, uPA, MMP-2, MMP-9." (PMID 31511625, 2019). "MSCs are known to express receptors for several chemokines and growth factors secreted by tumor cells like platelet-derived growth factor (PDGF), interleukin 6 (IL-6), leucine-37 (LL37), prostaglandin E2 (PGE-2), and stromal cell-derived factor 1 (SDF-1)." (PMID 31238944, 2019). "The binding of a natural ligand, Hsp105, found on the surface membrane of tumor-derived exosomes to TLR2 and TLR4, stimulates the secretion of IL-6 and PGE1." (PMID 31555295, 2019). "The other phenotype that they referred to as inflammatory CAFs (αSMA low) were found at a distance from tumor cells and had a lower ECM expression and a higher expression of inflammatory mediators, particularly IL-6." (PMID 30832219, 2019). "IL-6 has been shown to induce immune cell recruitment, modify the TME, and help tumor cells with functions such as survival, apoptosis, angiogenesis, invasiveness, and metabolism." (PMID 32039025, 2019).
tumor (continued). "Gene expression analyses performed on CD11b+ tumor infiltrating immune cells isolated from EONY#17 tumors showed enhanced expression of the M1-like markers IL1β, Cxcl9, IL6 and Nos2." (PMID 31519152, 2019). "It was also reported that ATLIII inhibits mast cell proliferation, upregulates anti-inflammatory cytokines, and inhibits pro-inflammatory cytokines such as IL-6, IL-8, IL-1β, and TNF-α in tumor microenvironment." (PMID 32038231, 2019). "A functional blockade of IL-6 signaling by Tocilizumab decreased pY-STAT3 by both myeloid cells and the different populations of T cells, leading to increased production of the tumor-immunity promoting cytokine secretion of IL-12 and IL-1β." (PMID 31861720, 2019). "In a search for the source of elevated salivary IL-6 levels in patients with OSCC, we investigated the expression of IL-6 protein in the tumor tissue." (PMID 31766212, 2019). "We have shown that in vitro Th17 cells differentiated with IL-6 and TGF-β and in vivo tumor-infiltrating Th17 cells express CD39 and CD73 ectonucleotidases." (PMID 31480382, 2019). "EREG is essential for the NF-CAF transformation needed to induce EMT of tumor cells in a JAK2-STAT3- and IL-6-dependent manner in OSCC." (PMID 31234944, 2019). "In contrast, IRIS-silenced or inactivated cells showed reduced tumor formation ability, limited MSC recruitment into tumors, reduced circulating IL-6 and PGE2 levels, and prolonged overall survival." (PMID 31014367, 2019). "The obvious upregulation of circulating EVs population in oral cancer patients positively correlated with IL-6 and TNF-α in tumor tissues." (PMID 30954079, 2019). "Multivariate analysis revealed that preoperative serum IL6 > 8.45 pg/ml, preoperative serum IL8 > 68 pg/ml, preoperative serum TNF − α > 14.9 pg/ml, microvascular invasion (MVI), and maximum tumor size > 6 cm were independent predictors of RFS." (PMID 31781194, 2019). "The concentrations of IL-6, IL-10, and TGF-β significantly increased in the ascites during tumor progression, as we showed in a previous study." (PMID 31753019, 2019). "In particular, IL-6 has been proven to activate NF-κB and STAT3 pathways to facilitate a tumour micro-environment." (PMID 30962499, 2019). "Through secretion of various cytokines (such as TGF-β, IL-6, CXCL14, etc.)into the tumour microenvironment, CAFs endow cancer cells with proliferative, invasive, and angiogenic properties." (PMID 30911001, 2019). "We elucidated an autocrine loop of IL-6/IGF-1R/STAT3 in EMT-mediated resistance and tumor growth in NSCLC." (PMID 31523190, 2019). "Consistent with pathological features, there was significantly higher expression of cytokines IL-6 (Il6) and TNFα (Tnfa), chemokines KC (Cxcl1), MIP2 (Cxcl2), and MCP1 (Ccl2), and tumor-promoting molecule COX2 (Cox2) in Nlrp12-/- HCC." (PMID 30990169, 2019). "Exosomes released from MM patients' BM-MSC modulate disease progression in vivo by increasing the exosome-based delivery of IL-6, CCL2 (C-C motif chemokine ligand 2), and fibronectin and decreasing expression of the tumor suppressor miR-15a." (PMID 31281380, 2019). "MiR-155-5p induces an increased secretion of IL-6 and IL-8, thereby promoting stemness, EMT, chemoresistance, and tumorigenicity of tumor cells." (PMID 31595161, 2019). "Tumor -produced CSF3, IL-1β, and IL-6 activate STAT3 in MDSCs which leads to their expansion but hinders MDSC maturation into macrophages or neutrophils." (PMID 31572387, 2019). "Moreover, it is well known that many cytokines, such as TNF-α, COX2, and IL6, can regulate carcinogenesis by affecting cell proliferation and apoptosis; thus, the production of cytokines was examined by quantitative real-time PCR (qRT-PCR) in the tumor tissues of Ct55 knockout and WT mice." (PMID 30944312, 2019). "IL-6 and FRA1 protein expression was increased in tumor compared with non-tumor tissues and positively correlated in the CRC cohort." (PMID 30804456, 2019).
tumor (continued). "It have been reported that CAF actively secret cytokine such as SDF-1, IL6, IL8 which remodel tumor stroma and positive regulate cancer progression." (PMID 31367190, 2019). "Collectively, these studies highlight the requirement for continued IL-6 production in the TME, as chronic IL-6 signaling is required to maintain DNMT1 expression and tumor promoter gene methylation and silencing." (PMID 31557902, 2019). "The release of IL-6, IL-8, and CXCL1 from endothelial cells is enhanced by VEGF through an autocrine effect thus creating a pro-inflammatory environment responsible for tumor progression." (PMID 31769418, 2019). "An environment of chronic inflammation yields IL-6, which promotes OSCC tumor growth and progression." (PMID 31572681, 2019). "Numerous studies have shown that tumor CDDP resistance can be provoked by several TAM-secreted cytokines, such as IL-6 and type I interferon (IFN)." (PMID 31450627, 2019). "Blockade of IL-6/STAT3 signaling attenuated the expression of CD44, CSC-like properties, and aggressive tumor behavior in vitro and in vivo." (PMID 31315262, 2019). "Together with IL-6, which is a representative molecule in inflammatory responses during progression of RCC, these growth factors modulate the tumor environment to improve its growth and dissemination." (PMID 29570259, 2019). "Activation of MDSC during tumorigenesis occurs via the release of factors either by activated T cells or tumor stromal cells including COX2, prostaglandins, IL-6, GM-CSF, VEGF, IFN-γ, IL-13, TGF-β." (PMID 31146452, 2019). "Oh and colleagues have clearly demonstrated that IL-6 production is strictly dependent on TG2 expression which, in turn, mediates the in vitro tumor sphere formation of ovarian cancer cells." (PMID 30691081, 2019). "Tumor-induced inflammation involving the IL-6/gp130/STAT3 and ERK5/STAT3 axes was shown to drive a pro-tumor transcriptomic program." (PMID 31766350, 2019). "Given that cytokines play critical roles in the proper establishment of anti-tumor immunity, we examined the levels of IFN-γ, IL-6 and IL-2 in both murine- and human-derived CD8+ T cells and in tumor cell coculture systems." (PMID 31511064, 2019). "Hence, NDV suppressed tumour growth may be through the impairment of IL-6 secretion." (PMID 30947706, 2019). "Of these molecules, IL-1β, IL-6, TNF-α, and IL-4 promote the phosphorylation of downstream proteins, e.g., NF-κB and STAT3, which then lead to inflammation, tumor proliferation, and prevention of apoptosis in cancer." (PMID 31781219, 2019). "For mice treated with CMS, serum levels of ROS and cytokines (IL-6, IL-1β, and COX2) significantly increased; the tumor grew faster in CMS-induced mice." (PMID 31396300, 2019). "Various tumor-derived factors have been reported to induce immature myeloid cells (CD33+ cells) to differentiate to MDSCs, these factors include prostaglandin E2, IL-6, IL-10, IL-1β, TGF-β, and proangiogenic factors such as vascular endothelial growth factor." (PMID 31620141, 2019). "In conclusion, the results indicated that MDSCs are induced mainly by HSCs through IL-6 signaling and produce inhibitory enzymes to reduce T-cell immunity and then promote HCC progression within the tumor microenvironment." (PMID 31614930, 2019). "Several signaling pathways have been reported as putative mechanisms involved in the anti-tumor function of MTF, including inhibition of pro-inflammatory cytokines similar to IL-6 and down-regulation of EMT markers such as E-cadherin, TWIST, ZEB, and Slug." (PMID 31337349, 2019). "IL-6 in the CC-MSC-conditioned media activated Stat3 through Jak2, and PI3K-Akt signaling pathways, that latter also being a pathway that promotes tumor cell survival." (PMID 31130595, 2019). "Our results indicated that Plasmodium infection significantly inhibits the tumor secretions of GMCSF, IL-10, IL-6, CCL-17, and CCL-22 in vitro through exosomes-like vesicles released by infected red blood cells." (PMID 30979375, 2019).
tumor (continued). "Essentially, interleukin 6 (IL6) and TGFβ promote tumor growth, IL6 together with TNFα facilitates invasion and metastasis, and TGFβ with IL10 suppresses the immune response against the tumor." (PMID 31921146, 2019). "Consistently, we found that Akirin2 overexpression upregulated, whereas endogenous Akirin2 knockdown eliminated VEGFA expression and angiogenesis through the IL-6/STAT3 signaling pathway, and thus facilitated tumor growth, invasion, and metastasis." (PMID 30886152, 2019). "In addition, it has been shown that an increased absolute platelet counts might reflect degree of the systemic inflammation induced by tumor, because pro-inflammatory mediators such as interleukin-2, interleukin-3, and interleukin-6 can stimulate the proliferation of platelet progenitor cells." (PMID 31921649, 2019). "This demonstrates that APEX1 promotes IL-6 and IL-8 expression in JHH6 cells, suggesting that it influences the tumor microenvironment." (PMID 31375000, 2019). "CAFs overexpress pro-inflammatory chemokines and cytokines such as IL-6, COX-2, and CXCL1, which mediate tumor-related inflammation and induce carcinogenesis." (PMID 31888563, 2019). "Taken together, these results strongly suggest that the levels of IL-6, DNMT3b/1, and OCT4 are highly correlated and that they play a role in early tumor recurrence and poor prognosis of HCC patients." (PMID 31771617, 2019). "Additionally, bortezomib attenuates the secretion of IL-6 and VEGF by endothelial cells and decreases vessel density in xenografts of squamous cell carcinoma, suggesting that bortezomib may target tumor-associated angiogenesis." (PMID 31739582, 2019). "IL-6 then activates the signal transducer and activator of transcription 3 (STAT3) pathway in immune cells, stromal cells, and tumor cells, which supports overall immune escape of cancer cells." (PMID 31409361, 2019). "By combining IL-6 inhibition with programmed death ligand-1 (PDL-1) targeted therapy in pancreatic adenocarcinoma, improved overall T-cell activation, and anti-tumor response was achieved in a murine model." (PMID 31683709, 2019). "Recent studies have shown that CAFs actively secret cytokines such as HGF, IL6, and SDF-1 which have positive effects on the cancer and the critical roles of TAMs in tumor progression are well documented." (PMID 30894509, 2019). "Finally, there is a lot of scientific evidence to support the use of minimally invasive surgical techniques since they don’t raise inflammatory reactants as much, and these findings may support the relationship between IL-6 and the type of tumor removal surgery found in our results." (PMID 31414667, 2019). "And they can modify TME that subsequently leads to tumour cell proliferation by producing proangiogenic factors (CXC12, VEGF, FGF, IL8/CXCL8, and PDGF-C), CCL-2, IL-6, FAP, IL-4, hyaluronan, IL-8, CXCL9, CXCL10, CXCL12, and Fsp1." (PMID 30944831, 2019). "When treated with exosomal Hsp70 and Hsp72, MDSCs was found to significantly increase the production of pro-inflammatory cytokines including IL-6, TNF- α, VEGF, and CCL2, leading to an increase in tumor growth and metastasis." (PMID 31555295, 2019). "However, IL-6 may also have an important anti-tumour role, for instance, by coordinating the transition from neutrophil to lymphocytes infiltration at the tumour bed, thus, leading to the resolution of inflammation and the initiation of T cell-mediated anti-tumour immunity." (PMID 31906092, 2019). "GO/KEGG analysis evidenced a significant enrichment of terms related to Th17 lymphocytes and in the KRAS-mutants enriched cluster the upregulation of IL6 and MMP12 has been detected, confirming the crosstalk between tumor and Th17 cells." (PMID 31405063, 2019). "Factors are involved in stimulating tumor angiogenesis indirectly by inducing VEGF, TGF-α and β, TNF-α, keratinocyte growth factor, insulin-like growth factor I (IGF-I), FGF, PDGF, and cytokines [interleukin (IL)-1α and IL-6 and EGF on tumor cells]." (PMID 31303863, 2019).
tumor (continued). "STAT3, a member of the JAK/STAT signaling pathway downstream from IL6/8, is highly expressed in TNBC and connected with tumor initiation, aggressive clinical behavior, unfavorable outcome, and resistance to chemotherapy." (PMID 31443516, 2019). "We found that IL-6 levels and OCT4/DNMT3b expression were positively correlated with early tumor recurrence in HCC patients." (PMID 31771617, 2019). "In the tumor mass, it is possible to detect an increase in the expression of IL1β, TNFα, and IL10 24 h after its inoculation, whereas IL6 expression increased earlier, just 12 h after cells injection." (PMID 31712726, 2019). "We examined the potential roles and related molecular mechanisms of IL-6 and STAT3 regarding the communication between tumour cells and ADSCs." (PMID 31196220, 2019). "Our study thus explains the role of IL-6 autocrine signalling in activating the STAT3 pathway in ADSCs and the effects of blocking IL-6 on the tumour-promoting activity of activated epidural ADSCs." (PMID 31196220, 2019). "IHC staining detected higher IL-6 levels in the tumor tissues of the MSC and IL-6 groups than in controls." (PMID 30755239, 2019). "In the COS-treated CRC group (CMCOS), COS protected mice from CRC by decreasing the disease activity index, tumor incidences and multiplicity, and the mRNA levels of COX-2, IL-6, TNF-α, IL-1β, IL-10, and IKK-β mRNA in colonic epithelial cells." (PMID 31620100, 2019). "As the antitumor effect of BCG-CWS was known to be mediated by the activation of the immune system and the induction of an inflammatory response, IL-6 production, and CD4 infiltration were evaluated by IHC after tumor tissues were harvested." (PMID 31817179, 2019). "Within the tumor microenvironment, IL-1β acts as a pleiotropic cytokine, increasing tumor growth and invasiveness via induction of MMPs, VEGF, IL-8, IL-6, TNFα, and TGFβ." (PMID 31174326, 2019). "Interleukin (IL)-6, which is one of the most important cytokines secreted by MSCs in the TME, plays an important role in regulating the immune response, tumor cell proliferation, tumor cell apoptosis, and tumorigenesis." (PMID 30755239, 2019). "Enhanced S1PR1 expression activates STAT3 and upregulates IL-6 expression, a proinflammatory cytokine crucial for STAT3 activation and inflammatory cell-mediated transformation and tumor progression." (PMID 31534132, 2019). "In fact, IL6/JAK/STAT3 signaling is expected to drive proliferation, survival, and invasiveness of tumor cells, and to suppress the anti-tumor immune response." (PMID 31357501, 2019). "The present collection of studies supports a second bi-directional interaction “IL-6/PGE2” between IRISOE TNBC tumor cells and MSCs in promoting aggressiveness in IRISOE TNBC tumor cells." (PMID 31014367, 2019). "A number of studies have highlighted the role of IL-6 and STAT3 in promoting tumor metastasis as their overexpression and/or hyper-activation have been reported in several human cancers." (PMID 30744595, 2019). "The recruitment of macrophages is often supported by CAFs and epithelial tumor cells, and is also stimulated by regulatory signaling pathways (e.g., NOTCH and IL6/STAT3)." (PMID 31569444, 2019). "Mimicking the effects of flagellin on cultured CRC cells, both IL6 and CCL2 were significantly increased in murine C26 cancer tumors when compared with the C26 tumor cells from which the C26 tumors originated." (PMID 31731747, 2019). "And the expression of IL‐6, IL‐1β, TNF‐α and MMP9 in tumor samples were also markedly up‐regulated compared with non‐tumor parts." (PMID 30903649, 2019). "Hypoxia upregulates some inhibitory signals for anti-tumor immune response such as PD-L1, indoleamine 2, 3-dioxygenase (IDO), interleukin-6 (IL-6), and interleukin-10 (IL-10)." (PMID 30925919, 2019). "In vivo, EREG expression in stroma fibroblasts promoted tumor growth with high stromal α-SMA, phospho-JAK2/STAT3, and IL-6 expression and upregulated EMT in HSC3 cells." (PMID 31234944, 2019).